CXCL9 (C-X-C motif chemokine ligand 9)
Diseases named in the same sentence as CXCL9 in open-access papers (continued):
Sharing a sentence is not in itself a finding about the gene and the disease.
breast cancer (continued). "In the same study, PGE2 suppressed IFNγ-induced CXCL9 levelsin MCF-7 and MDA-MB 231 breast cancer cells, and COX inhibitors increased CXCL9secretion." (PMID 24004819, 2013). "COX-2 inhibition increases release of CXCL9 and CXCL10 proteins from breast cancer cells and induces IL-8 down-regulation." (PMID 23405235, 2013). "In this study, we have identified the COX pathway as a potential pharmacologic candidate to enhance the intratumoral accumulation of CXCL9 and CXCL10 levels in breast cancer." (PMID 22333315, 2012). "In human breast cancer tissue specimens there is an inverse correlation between COX-2 overexpression and CXCL9 concentration, suggesting that the observed in vitro effects are of importance in vivo as well." (PMID 22333315, 2012). "CXCL9 and CXCL10 were not released into the culture medium of unstimulated MCF-7 or MDA-MB 231 breast cancer cells, whereas IFN-γ induced both cell types for CXCL9/10 secretion in a dose-dependent manner." (PMID 22333315, 2012). "Our results demonstrate that PGE2 inhibits, whereas COX inhibitors induce the release of CXCL9 and CXCL10 from breast cancer cells." (PMID 22333315, 2012). "We now demonstrate that PGE2 inhibits IFN-γ induced CXCL9 and CXCL10 secretion from breast cancer cells and that, conversely, the COX inhibitors acetylsalicylic acid (ASA) and indomethacin augment this release." (PMID 22333315, 2012). "Suppressing endogenous PGE2 synthesis by cyclooxygenase inhibition increases CXCL9 and CXCL10 release from breast cancer cells and is therefore a pharmacologic candidate to enhance intratumoral immune infiltration." (PMID 22333315, 2012). "To investigate the role of CXCL9 + macrophages in breast cancer, we conducted in vitro co-culture experiments using conditioned media from M0 macrophages, M1 macrophages, and siCXCL9 M1 macrophages, which were applied to MDA-MB-231 breast cancer cells." (PMID 41325308, 2025). "Increased levels of CCL7, CXCL9, and CXCL10 were found in the plasma of breast cancer patients." (PMID 39684443, 2024). "In this study, we showed that TI-NK cells act as major contributors to early CCL5/IFN-ɣ production along anti-HER2 antibody treatment in primary breast cancer patients, disclosing the role of the IFN-ɣ/CCL5/CXCL9 axis in the effectiveness of neoadjuvant treatment with anti-HER2 antibodies." (PMID 38167224, 2024). "EMID1 is more than lung cancer and lung injury; however, no study has found a relationship between CXCL9 and breast cancer." (PMID 39493752, 2024). "CXCL9 is also upregulated in the early stage of TNBC, which is consistent with previous research showing that it is highly expressed in patients with early breast cancer." (PMID 38957805, 2024). "High CXCL9 and CXCL13 levels conferred an improved prognosis in early breast cancer." (PMID 35468838, 2022). "In addition, the analysis in GEPIA2 revealed that higher CXCL9 levels were related to longer OS (P<0.01) and DFS (P<0.05) in breast cancer." (PMID 34527583, 2021). "Two groups of breast cancer datasets, GSE137356 and GSE18728, were used to determine if CXCL9 and CXCL13 expressions could predict chemotherapy response." (PMID 33815462, 2021). "Moreover, we demonstrate that a subset of breast cancer cells with high metastatic potential expresses the cell surface receptor CXCR3, which binds CXCL9/10." (PMID 32198421, 2020). "Although breast cancer cells express IL-1R, they did not respond to IL-1 treatment by upregulating CXCL9/10 like fibroblasts." (PMID 32198421, 2020). "Importantly, expression of CXCL9 and CXCL10 correlated markedly in dissected distant metastases samples from breast cancer patients, indicating co-expression of these cytokines in human metastasis." (PMID 32198421, 2020). "Indeed, both CXCL9 and CXCL10 promoted sphere formation and lung colonization by breast cancer cells." (PMID 32198421, 2020).
breast cancer (continued). "Recently, it was shown that neutralizing TIM-3, which is expressed on many cell types under homeostatic conditions but is restricted to CD103+ cDC1 inside the tumor, promotes CXCL9 expression by these cells and indirectly enhances the CD8+ T cell response in a breast cancer model." (PMID 30949170, 2019). "Indeed, a critical role for CXCL10 and to a lesser extent CXCL9 and CXCL11 was found in promoting breast cancer development." (PMID 29379506, 2017). "AMG487 inhibits CXCR3 signaling by obstructing binding of CXCR3 ligands and has been shown to inhibit in vitro CXCR3-mediated cell migration by the CXCR3 chemokines, CXCL9, CXCL10, and CXCL11, and to inhibit lung metastasis in a mouse model of metastatic breast cancer." (PMID 25798946, 2015). "PGE2 inhibits IFN-γ-induced release of CXCL9 and CXCL10 in human breast cancer cells." (PMID 22333315, 2012). "IFN-γ exposed breast cancer cells were used as controls in the subsequent experiments, because IFN-γ is a strong inducer of CXCR3 ligand expression, and the anti-tumor effects of CXCL9 and CXCL10 have been shown to be IFN-γ dependent in mouse models." (PMID 22333315, 2012). "In addition, integrating pathway and gene information, we identified five (ID4, ANXA4, CXCL9, MYLK, FBXL7) and six (SQLE, E2F1, PTTG1, TSTA3, BUB1B, MAD2L1) known cancer genes significant for ovarian and breast cancer respectively." (PMID 22759382, 2012). "The COX-2 inhibitor, indomethacin, increases the expression of CXCL9/10 in EOC cells; a phenomenon also observed in breast cancer (BC)." (PMID 35269786, 2022). "Using a syngeneic mouse model of breast cancer, here, we found that SRC-3 inhibition by SI-2 treatment and SRC-3 knockdown generated tumor-suppressing TIME by recruiting cytotoxic immune cells changing through Cxcl9 elevation in breast tumors to aid in the suppression of breast tumor progression." (PMID 36316775, 2022). "Furthermore, CXCL9 and IDO1 have been shown to be prognostic markers in breast cancer." (PMID 24495478, 2014). "To study the release of the two chemokines CXCL9 and CXCL10 from breast cancer cells we investigated regulation of protein secretion by supplying the inflammatory cytokines IFN-γ and TNF-α, which are both present in breast cancer tissues and known to induce CXCR3 ligands in other cell types." (PMID 22333315, 2012). "In addition, CAFs provide CXCL9 and CXCL10 to contribute to the CSC phenotype and proliferation of metastatic breast cancer cells, which bind to CXCR3 and activate JNK-IL-1 signaling in breast cancer cells; thus, a positive loop is established and MAFs are further activated." (PMID 34112258, 2021). "Among the inversely correlated genes were four chemokines, CCL5, CXCL9, CXCL10 and CXCL11 indicating that IRX2 might be actively involved in the regulation of chemokine secretion by mediating the transcriptional repression of these chemokines in breast cancer cells." (PMID 26560478, 2015). "In this context, it might be interesting to analyze tumor tissue samples of breast cancer patients that took NSAIDs on a regular basis to see if CXCL9 expression is different from patients who did not, but such investigations were not in focus of the analysis presented." (PMID 22333315, 2012). "Conversely, in the lung cancer and breast cancer cohorts, SIN3B did not exhibit any correlation with CXCL9/10/11 or CD8A." (PMID 39316363, 2024). "This is in agreement with clinical studies in human breast cancer identifying CXCL9, rather than CXCL10 or CXCL11, as a potential biomarker for diagnosis of breast cancer and therapy response, suggestive of its protective role in breast cancer biology." (PMID 22333315, 2012).
viral infection (61 papers, 2004 to 2026). "Comparing mAbs of IgG2a subclass, we detected enhanced secretion of the viral infection-associated chemokine CXCL9 by IC composed of the lowest affinity IgG2a mAb." (PMID 38664730, 2024). "Upregulation of the Stat1-mediated response to the virus, interferon response, immune system activation, and ISGs, such as Rsad2, IFITM3, Cxcl9, Bst2, and Oas2, across all strains confirmed ongoing viral infection." (PMID 39875898, 2025). "Upregulation of the Stat1-mediated response to the virus, interferon response, immune system activation, and interferon-stimulated genes (ISGs; e.g., Rsad2, IFITM3, Cxcl9, Bst2, and Oas2) across all strains confirmed ongoing viral infection." (PMID 39875898, 2025). "In viral infections, CXCL9 together with CXCL10 play a fundamental role by attracting activated T cells via CXCR3." (PMID 38664730, 2024). "Elevated levels of CXCL9 and CXCL10 are linked to the Th1 immune response due to bacterial and virus infection." (PMID 37528399, 2023). "In contrast, a significant difference was found between both experimental groups for the expression of IL-6, IP10, and CXCL9 7 days after virus infection." (PMID 38143489, 2023). "Yet, it is also conceivable that upon viral infection Cxcl9+ FRCs represent LNSCs that can acquire anti-viral properties, which was simulated by Irf3 and Irf1 overexpression in the MSC cell line." (PMID 36433946, 2022). "Conversely, under viral infection we found that CXCL9 is increased in the KD/KO cells at later timepoints compared to WT." (PMID 35085371, 2022). "Urothelial expression of CXCL9/10 in response to BKPyV-infection will recruit host immune cells into the tissue, which release IFNγ to start a cascading reaction that limits viral infection." (PMID 35194151, 2022). "Specifically, CXCL9, as a core regulator for immune responses against viral infection, has been reported to be significantly up-regulated during SARS-CoV-2 infection." (PMID 33505977, 2020). "CXCL9, is also induced by IFN-γ in macrophages, implicated in cancer inflammation and viral infections, and participates in T-cell trafficking, chemotaxis, and activation." (PMID 31836011, 2019). "It has been reported that CXCL9 gene expression is elevated after stimulation of mouse monocytes, neutrophils and hepatocytes by interleukin γ and viral infection." (PMID 23875831, 2013). "Others have found lower levels of CXCL9 in the aged setting following viral infection." (PMID 36802099, 2023). "Single-cell sequencing, tissue immunofluorescence staining, and adoptive transfer experiments indicate that viral infection-induced type I IFN signaling could inhibit CXCL9/10 production in myeloid cells, ultimately impairing pulmonary migration of Mtb-specific CD4+ T cells." (PMID 35672321, 2022). "While the increase of Cxcl9+ FRCs upon viral infection is well documented, it remains unclear if Cxcl9+ FRCs represent a unique subset that is rapidly expanded upon infection or a transient state which Ccl19+ FRCs can enter during inflammatory immune responses." (PMID 36433946, 2022). "Therefore, it is conceivable that the decrease in CXCL9 levels in the lungs of coinfected mice was due to directly elevated type I IFN levels induced by viral infection followed by perturbation of Mtb-specific T cell migration from the LN to the pulmonary infection site." (PMID 35672321, 2022). "With aging we found reduced levels of CXCL9, a chemo-attractant mostly secreted by macrophages, and responsible for the recruitment of lymphocytes during viral infections which could explain the reduced numbers of lymphocytes recruited to dLN and/or infected joints." (PMID 27736984, 2016). "The CXCL9/10/11-CXCR3 chemokine axis plays a role in autoimmunity, cytotoxic T cell recruitment to tumor sites, and viral infection." (PMID 41516395, 2026). "IFNγ-inducible chemokines CXCL9 and CXCL10 are sourced from pro-inflammatory M1 macrophages in models of viral infection." (PMID 41516395, 2026).
viral infection (continued). "CXCL9 and CXCL10 were identified among DEGs and are host response factors to viral infection downstream of IFNγ." (PMID 41516395, 2026). "CXCL9 and CXCL10 are type 2 interferon-inducible chemokines secreted by macrophages in response to viral infection." (PMID 41516395, 2026). "While the expression of CXCL9 and CXCL10 has been used as a surrogate for IFN-I expression, these ligands can be induced during acute and chronic viral infection or recall responses by both type I and II IFNs." (PMID 40062995, 2025). "The expression of CXCR3 ligands, CXCL9 and CXCL10, is key IFN-induced environmental cues that regulate T cell positioning and function during acute and chronic viral infection, and recall responses." (PMID 40062995, 2025). "Thus, spatial analyses suggest that the CXCR3 and CXCL9/10/11 axis facilitates interaction of innate and adaptive immune cells in lymphoid tissue, which may shape both the position and characteristics of memory B cells during viral infection." (PMID 40964019, 2025). "In detail, levels of CD177, a marker for neutrophil activation, and CXCL9 were elevated, while DDX58, also known as RIG-I, a sensor for a viral infection that induces type I IFN production, was found to be decreased in aIFNpos patients." (PMID 38421006, 2024). "Viral infection induces a variety of proinflammatory cytokines and chemokines including IL-1b, IL-6, TNFa, CCL2, CCL3, CXCL1, CXCL2, CXCL9 and CXCL1034,35." (PMID 38750107, 2024). "CXCR3 and its ligands CXCL9, CXCL10 and CXCL11 are known to regulate leukocyte recruitment during numerous viral infections." (PMID 39803542, 2024). "Now, there are studies which pointed out that IL-27 can inhibit viral infection by activating STAT1/3 and CXCL9/10." (PMID 35785034, 2022). "CXCL9, also upregulated in the shortened NIS group, plays an important role in controlling viral infection." (PMID 36211387, 2022). "In summary, aging impairs mDC accumulation in the dLN during virulent or attenuated viral infection, leading to decreased IFN‐γ production by G1‐ILCs and impaired CXCL9 expression by uninfected iMOs, culminating in reduced NK cell recruitment to the dLN." (PMID 32657004, 2020). "At day 2 postinfection, both TNF-α and IL-6 transcripts were moderately induced by wild-type virus, while CCL2, CCL4, CXCL9, and CXCL10 mRNA levels were all highly elevated by wild-type virus infection." (PMID 29138302, 2017). "Microglial cells have been shown to produce high levels of the chemokines CXCL9 and CXCL10 in response to viral infection." (PMID 28407741, 2017). "Microglial cells were found to produce high levels of CXCL9 and CXCL10 in response to viral infection, while infected astrocyte cultures produced markedly lower levels." (PMID 27207308, 2016). "Activated endothelium can also secrete proinflammatory cytokines and chemokines such as IL-6, MIG/CXCL9, IP-10/CXCL10, type I and type II IFNs, MCP-1/CCL2, and TNF-α in response to a virus infection." (PMID 26965109, 2016). "The serum concentrations of the CXCL9 and CCL2 chemokines appear to be unaffected by pregnancy and tend to be poorly induced by influenza-like or H1N1pdm2009 viral infection." (PMID 25254368, 2014). "A curious observation was the inverse correlation of the expression levels of the transcripts of IL-6, TNF-α, CXCL9, CCL2 and CCL3 and the virus infection dose." (PMID 24086645, 2013). "Although the ligands of CXCR3—CXCL9, CXCL10, and CXCL11—are key ISGs, it is unknown how blocking IFNAR during viral infection impacts chemokine expression for preferential formation of TSCM cells." (PMID 40062995, 2025). "CXCL9 is induced by IFN-γ in macrophages and is involved in cancer and viral infections." (PMID 37493737, 2023). "The formation of super-enhancers governing CXCL9/10/11, CCL7/8/13, IFITM1/2/3, OAS1 genes, but not housekeeping genes, was robustly decreased in SAFA mutation cells after virus infection." (PMID 35658050, 2022).
viral infection (continued). "Upregulated expression of cytokines, chemokines and growth factors was commonly observed in patients and animals with lymphopenia induced by viral infection, including IL-2, IL-6, IL-12, IL-18, IL-1β, IFN-γ, CCL2/MCP-1, CXCL1, CXCL8/IL-8, CCL3/MIP-1-α, CCL7/MCP-3, CXCL10/IP-10 and CXCL9/MIG." (PMID 34578457, 2021). "Similarly, the expression of the chemokines Cxcl9 and Cxcl10 by TLR3 tolerized macrophages correlates with the role of these factors in CD8+ T cell recruitment to sites of viral infection, cells that have a critical anti-viral activity." (PMID 29867935, 2018). "CXCL-9 and CXCL-10 are STAT1-dependent inflammatory factors induced by different cell populations in response to interferons and IL-27, and their expression correlates with the induction of interferon-stimulated genes (ISGs) which promote an antiviral state to control viral infections." (PMID 40711072, 2025). "Although accumulating evidence have supported the redundant functions of CXCL9 and CXCL10 in controlling recruitment, differentiation and proliferation of immune cells in various disease, such as tumor development and viral infections, their activities in S. aureus infection remain unclear." (PMID 39001897, 2024). "Similarly, although CXCL9 and CXCL10 expression are vital to the host’s response to CNS viral infections, persistent increases in astrocyte secretion of CXCL10 correlated with increased disease severity, while CXCL10 neutralization improved neurological outcome." (PMID 26860080, 2016). "In addition, production of CXCL9/10 might be important for positioning tumor-infiltrating T cells in cDC1-rich areas and facilitating local T cell restimulation, similar to the positioning of memory CD8+ T cells by CXCL9 in lymph nodes upon viral infection." (PMID 30352680, 2018). "Additionally, PDCoV infection increased the transcription of the chemokines CCL2, CCL4, CXCL9, CXCL10 and CXCL11, suggesting that these chemokines may contribute to the recruitment and regulation of macrophages or other inflammatory cells to the sites of virus infection." (PMID 35328701, 2022). "The results presented here demonstrate that the chemokines CXCL9 and CXCL10 were produced in response to viral infection of microglial cells, but not in response to viral infection of primary astrocytes." (PMID 27207308, 2016).